RB1 (RB transcriptional corepressor 1)
Diseases named in the same sentence as RB1 in open-access papers (continued):
Sharing a sentence is not in itself a finding about the gene and the disease.
glioblastoma (continued). "The relative expression of the RB1 transcript was 1.6-fold lower in glioblastoma samples compared with grade II samples and 1.4-fold lower compared with grade III samples." (PMID 26317630, 2015). "This includes deletions of known tumour suppressors such as RB1 and NF1, but also more novel glioblastoma associated genes." (PMID 24548782, 2014). "Primary glioblastomas exhibit frequent EGFR amplification, homozygous deletion of CDKN2A and p14ARF, CDK4 amplification, MDM2 or MDM4 amplification, RB1 mutation/homozygous deletion, monosomy 10 and PTEN mutation." (PMID 19333441, 2009). "LOH at the RB1 locus has been found in 25–45% of glioblastomas and in about 25% of anaplastic astrocytomas (AA), as well as in bladder carcinomas, and malignant neuroendocrine lung carcinomas." (PMID 12556968, 2003). "The RB1 gene is typically downregulated in glioblastoma, contributing to cell cycle progression." (PMID 38674436, 2024). "Furthermore, CDKN2A (1.20% of cases) and RB1 (1.03% of cases) are hallmarks of lung squamous cell carcinoma and glioblastoma respectively." (PMID 28155630, 2016). "Here, we found that several of the most frequently mutated genes in glioblastoma including: EGFR, PTEN, NF1, PIK3R1, RB1, PDGFRA and QKI possessed high 5 hmC levels across intronic regions and further loss of 5 hmC in tumours may reflect a loss of genome integrity." (PMID 27886174, 2016). "Meantime, RNF12 interacted with and ubiquitinated RB1 to induce its degradation, which activated the MAPK signalling pathway to promote the proliferation of glioblastoma." (PMID 37132043, 2023). "The RB signaling pathway was affected in 77% of glioblastomas sampled, including alteration of CDKN2 A/B, CDK4, CDK6, CCND2, and RB1 genes." (PMID 35052830, 2022).
glioblastoma (continued). "MiR-7 was down-regulated in glioblastoma which inhibited invasiveness of primary glioblastoma lines, while miR-26 promotes glioblastoma cell proliferation in vitro and tumor growth in vivo by targeting several tumor suppressor genes such as PTEN and RB1." (PMID 22442669, 2012). "In non-TCGA patients with glioblastoma, receipt of chemotherapy (HR: 0.20), methylated MGMT (HR: 0.42), 21q loss (HR: 0.54), 19q gain (HR: 0.72), and RB1 alteration (HR: 0.77) positively affected survival." (PMID 39164213, 2025). "It has been demonstrated that in glioblastoma, ID2 can bind to RB1 and thus inhibit its function." (PMID 38254880, 2024). "A major point how this effect of miRNA-21 on glioblastoma might be mediated is the initially mentioned P15/P16/RBI/E2F pathway, especially RB1, with is a direct target of miRNA-21." (PMID 39335591, 2024). "Furthermore, RNF12 was found to interact with and target RB1 for degradation to stimulate the MAPK pathway and promote the malignant proliferation of glioblastoma." (PMID 37132043, 2023). "None of the de novo RRD glioblastomas (0/9, 0%) had CDK4 amplification, and two tumors had truncating mutations in RB1 (2/9, 22%)." (PMID 38079020, 2023). "Also, allelic losses on 19q and 13q, promoter hypermethylation of the RB1 gene, and overexpression of PDGFRA are more common in secondary glioblastomas." (PMID 19333441, 2009). "Finally, GSK3B, PNKP and RB1, which were suggested as targets to control the neuroinflammation in response to WNV infection in the glioblastoma cell line U251, were not modulated in our study." (PMID 32374750, 2020). "KNS42 glioblastoma cells, by contrast, contained no genuine amplifications, but instead its highly rearranged genome harboured low-level copy number gains at loci such as 3q26 (PIK3CA), and hemizygous deletions at known tumour suppressor loci such as 13q14 (RB1)." (PMID 19365568, 2009).
melanoma (104 papers, 1996 to 2025). A malignant, usually aggressive tumor composed of atypical, neoplastic melanocytes. "Another cancer-associated gene found to have increased UV susceptibility in RB1 KO cells, and mutation rates in melanoma, is TPTE." (PMID 34983823, 2022). "Using sequencing datasets from 1,970 melanomas, we found that cancers with RB1 pathway mutations, including CDKN2A/p16, have significant co-occurrence of mutations in TERT and TPTE." (PMID 34983823, 2022). "Concurrent inactivation of PTEN and RB1 have previously been described as a mechanism for loss of BRAF/MEK dependence in BRAFV600E mutated melanomas and the cell cycle progression pathway including RB1 have been associated to BRAF inhibitors resistance." (PMID 30899440, 2019). "The deletion of CDKN2A and loss of p16INK4A protein was shown to predict sensitivity of melanoma cell lines to Palbociclib, while loss of RB1 led to drug resistance." (PMID 27409346, 2016). "A number of signal transduction and cell cycle regulatory pathways have been implicated in the etiology and progression of melanoma, including the retinoblastoma (RB1) and p44/42 mitogen-activated protein kinase (MAPK) pathways." (PMID 20140953, 2010). "Correspondingly, TERT mutations are significant elevated in melanomas with RB1 pathway alterations." (PMID 34983823, 2022). "Moreover, cooperation between Mitf and the retinoblastoma protein Retinoblastoma 1 (Rb1) potentiates Mitf to activate transcription, which leads to dysregulation of the cell cycle and causes melanoma in humans." (PMID 30544544, 2018). "Individuals harboring a germline RB1 gene mutation are predisposed to the development of several other cancers throughout life including bone and soft tissue sarcomas, melanoma, brain tumors and have a 50% risk of transmitting their germline RB1 gene mutation to offspring." (PMID 20844677, 2010). "For instance, DNMT3A and SUV39H1 promote the methylation of CpG islands in the RB1 promoter, leading to reduced RB1 expression and enhanced cancer cell growth, as observed in melanoma." (PMID 40070134, 2025). "The gene PRDM2 showed a mutation pattern of mutual exclusivity with CDKN2A and is of particular interest since PRDM2 is a binding partner of RB1, a well‐established melanoma driver." (PMID 36219477, 2023). "In other cancers like melanoma, the frequency of pocket protein paralogue alterations is comparable (melanoma RB1 = 5.6%, RBL1 = 5.9%, RBL2 = 3%)." (PMID 35368709, 2022). "For example, the retinoblastoma gene (RB1) regulated a series of malignant processes in melanoma cells, such as cell proliferation, differentiation, migration, and invasion." (PMID 34745259, 2021). "RB patients with germline RB1 mutation who received EBRT have a high risk of 50% to develop SPMs with advanced age including leiomyosarcoma, OS, melanoma, lung, and bladder cancer." (PMID 34073340, 2021).
melanoma (continued). "A total of 9 patients (3.4%) carried mutations in high-to-moderate melanoma risk genes (CDKN2A, POT1, ACD) and 22 (8.3%) patients in other cancer syndrome genes (NBN, BRCA1/2, CHEK2, ATM, WRN, RB1)." (PMID 33050356, 2020). "In vitro studies using a vemurafenib-resistant melanoma A375 cell line have shown a lower expression of RB1 transcripts and pRB than the vemurafenib-sensitive A375 cells." (PMID 30899440, 2019). "Using TEAZ, we created a highly aggressive melanoma model via Cas9-mediated inactivation of Rb1 in the context of BRAFV600E in spatially constrained melanocytes." (PMID 30061297, 2018). "Inherited mutations cause a genetic predisposition to melanoma, including mutations in cell cycle genes such as CDKN2A, CDK4, RB1 and MDM2, as well as melanocyte differentiation and activation genes such as MC1R, TYR, TYRP1 and ASIP." (PMID 22536322, 2012). "The CDKN2A protein controls passage through the G1 checkpoint of the cell cycle by inhibiting the phosphorylation of the RB1 protein and of the three tumor suppressors at this locus is the one longest recognized to have a significant role in melanoma." (PMID 20140953, 2010). "Interestingly, our study of human melanoma A375P cells reveals that AT-9283 disrupts the G1-to-S-phase transition by inhibiting Rb1 protein phosphorylation, resulting in a significant decrease in the G2/M and S populations of the cell cycle." (PMID 38474202, 2024). "Additionally, melanoma risk is increased in mixed cancer syndromes caused by mutations in PTEN, BRCA2, BRCA1, RB1 and TP5330." (PMID 36805510, 2023). "For example, the RB1 pathway is a primary driver of skin cancers, with mutations in RB1, CDKN2A/p16, CDKN1A/p21, CDKN1B/p27, CDKN2B/p15, CCNE1/cyclin E, and CCND1/cyclin D, collectively, in 26.4% of melanomas." (PMID 34983823, 2022). "An increased melanoma risk has been documented in carriers of germline mutations causing other cancer syndromes, including hereditary breast and ovarian cancer (BRCA1/BRCA2), retinoblastoma (RB1), or xeroderma pigmentosum (XPs)." (PMID 33050356, 2020). "In mouse melanoma cells Rb1 cooperates with MITF to activate expression of Tyr and Cdkn1a/p21Cip1." (PMID 32850962, 2020). "Decreased expression of Cyclin D1 and RB1 proteins has previously been reported in melanoma." (PMID 21615965, 2011). "Further analyses into the specific mutated regions of TERT identified upstream promoter, downstream, and intronic regions as having increased mutation frequency in melanomas that also carry mutations in the RB1 pathway compared with tumors without RB1 pathway alterations." (PMID 34983823, 2022).
melanoma (continued). "Additionally, resveratrol treatment inhibited SG-mediated Rbfox2 localization, further inhibiting RB1 protein expression, and inhibited specific Rbfox2 localization to the cytoplasm in melanoma B16-F10 cells, thereby effectively inhibiting metastasis and tumor growth ability." (PMID 31028247, 2019). "It was interesting that eleven of the molecules previously implicated in melanoma pathogenesis (described in the introduction) were identified as hubs in the Bayesian gene networks generated from our A375 cell dataset, including: BRAF, CCND1, RB1, PTEN, TYR, CDKN2A, and SOX10." (PMID 22536322, 2012). "The most mutated genes, which are associated with the development of resistance to targeted therapy in melanoma include CDKN2A, RB1, PIK3CA, AKT3, HOXD8, PAX5, MAP3K8, and MITF." (PMID 38275910, 2024). "In melanoma, SGs mediate RNA binding fox-1 homolog 2 (RBFOX2) localization and further promote retinoblastoma 1 (RB1) protein levels along with mRNA expression, thus significantly promoting melanoma cell metastasis and tumor growth." (PMID 37179344, 2023). "Conversely, depletion of SUV39H1 in melanoma cells leads to RB1 activation and reduced E2F1 transcriptional activity, inhibiting melanoma development." (PMID 35163453, 2022). "SUV39H1/DNMT3A-dependent methylation of the RB1 promoter stimulates PIN1 expression and melanoma development." (PMID 33234142, 2020). "Moreover, RB1 mRNA expression was assessed in two melanoma cell lines (SKMEL-5 and COLO829) after 3 days of vemurafenib treatment and the most sensitive SKMEL-5 cells presented the highest RB1 expression compared to COLO829 cells." (PMID 30899440, 2019). "The results showed that GPD, but not Rb1, inhibited cell proliferation and anchorage-independent melanoma cell growth in a dose-dependent manner." (PMID 25137374, 2014). "To determine whether GPD can affect melanoma cell growth, we first investigated the effects of GPD and Rb1 on SK-MEL-28 cell proliferation." (PMID 25137374, 2014). "However, similar intragenic deletions in RB1 and PTEN were recently described in melanoma cell lines (SKMEL-207, A2058, and SKMEL-178), suggesting that these types of micro-genomic events are present in other cancers." (PMID 23284754, 2012). "Despite MITF acts together with many transcription factors as SOX10, YY1, TFAP2A, LEF1, RB1, IRF4, and PAX3, its activity level determines the phenotype adopted by melanoma cells, whether invasive, proliferative, or differentiated according to the MITF rheostat model." (PMID 32850962, 2020). "To assess the mechanisms of the RIPK4-mediated regulation of cell proliferation in melanoma, we examined whether downregulation of RIPK4 affects the levels of important proteins involved in cell cycle regulation, that is, the cyclin-dependent kinases and retinoblastoma protein (RB1)." (PMID 36765875, 2023).